ALB (albumin)
Diseases named in the same sentence as ALB in open-access papers (continued):
Sharing a sentence is not in itself a finding about the gene and the disease.
cancer (continued). "Sixty-one patients (52.1%) had an Index4 score of 0, defined as all of the following: ECOG PS 0 or 1, creatinine clearance above 40 mL/min, albumin above 35 g/L and stage 1 to 3 cancer." (PMID 36658198, 2023). "A growing body of evidence supports the role of FcRn in cancer therapeutics, particularly in albumin-based pharmacokinetics and antitumoral activity through antigen-presenting mechanisms." (PMID 38132243, 2023). "Due to the close connection between albumin and nutrition, the level of albumin has been commonly measured in the treatment of advanced cancer to estimate patient prognosis." (PMID 37793977, 2023). "Another approach is the production of nab-PTX (Abraxane®), composed of the lipophilic drug PTX, conjugated to albumin at a high pressure, being used to treat several types of cancer." (PMID 37836018, 2023). "The combination of nanoparticle albumin-bound paclitaxel (nab-PTX)/paclitaxel (PTX) with immune checkpoint inhibitors (ICIs) has demonstrated significant efficacy in cancer patients." (PMID 37520574, 2023). "Several review articles have been published that detail the methods for producing albumin-based nanoparticles and their potential use in overcoming drug resistance for various types of cancer." (PMID 37836018, 2023). "NPS combines NLR, lymphocytes and albumin, and other biomarkers to link the effects of cancer, nutrition, inflammation, and immunity and has a powerful prognosis prediction function." (PMID 37743468, 2023). "Low serum albumin level had also been reported to be related with poor prognosis in many types of cancer." (PMID 36635689, 2023). "In advanced cancers, serum albumin levels are frequently used as a laboratory parameter to indicate symptoms related to inflammatory response or cancer cachexia." (PMID 37787070, 2023). "Next, we used MDA-MB-435s, a human cell line, to evaluate the anti-cancer effects of albumin–chlorogenic acid NPs." (PMID 37176983, 2023). "Serum albumin level serves as a vital parameter in clinical practice for evaluating the nutritional status of patients afflicted with malignant tumors." (PMID 37787070, 2023). "Low albumin level, smoking and history of cancer have emerged as new predictors of mortality over an extended follow-up period." (PMID 37198577, 2023). "Our results denote albumin–chlorogenic acid NPs can be used as an effective candidate for anti-microbial and anti-cancer applications; however, further in vivo confirmatory studies are warranted." (PMID 37176983, 2023). "NanoPcM, a pH-sensitive photothermal nanomaterial, was constructed through the self-assembly of morpholine-modified silicone phthalocyanine (PcM) and serum albumin for cancer-targeted photodynamic immunotherapy." (PMID 36986636, 2023). "Overall, while further research is required to comprehensively comprehend the potential anti-cancer effects of 2S albumin, this protein shows promise in potentially inhibiting cancer cell invasion and migration." (PMID 37987317, 2023). "Prognostic nutritional index (PNI), which is calculated from serum albumin level and total lymphocyte count, was suggested as a simple and practical screening tool for predicting prognosis in patients with cancer." (PMID 36678182, 2023). "It has been demonstrated that SPARC promotes intratumoral aggregation of albumin-bound nanoparticles, and nab-paclitaxel utilizes this characteristic of cancer biology, as it is preferentially retained by tumoral SPARC." (PMID 37509639, 2023). "Covariates, including BSA, age, sex, albumin, total protein, and cancer type, were identified as statistically significant predictors of FCN-159 disposition." (PMID 36755948, 2023). "F. cretica methanolic extracts were formulated at nano-scale for green synthesis of silver nanoparticles, albumin conjugation and liposomes encapsulation to enhance targeted bioactivity against cancer." (PMID 36635434, 2023).
cancer (continued). "In contrast to the changes reported in patients with cancer, both plasma albumin and AGP levels tend to decrease throughout pregnancy." (PMID 38140068, 2023). "The Glasgow Prognostic Score includes both C-Reactive Protein (CRP) and albumin levels to predict survival in patients with cancer, and these biomarkers have been incorporated in other palliative prognostication tools as well." (PMID 37880704, 2023). "Prognostic nutritional index (PNI), calculated from serum albumin level and total lymphocyte count, has been developed as a prognostic marker for cancer patients." (PMID 36678182, 2023). "Fmoc-FF nanogels, endowed with a diameter of ~130 nm and a zeta potential of ~−20.0/−25.0 mV, enter cancer cells via caveolae, mostly those responsible for albumin uptake." (PMID 36986886, 2023). "Serum albumin (ALB) and hemoglobin (HGB) are important serum biochemical indices of the nutritional status of patients and are associated with cancer development." (PMID 37875880, 2023). "Albumin-based drug carriers involved in treating diabetes, hepatitis, arthritis, cancer and viral disease are commercially available." (PMID 36850121, 2023). "Previous studies had demonstrated that elevated LDH and decreased albumin were correlated with poor survivals in many kinds of cancers." (PMID 37770882, 2023). "It has been well recognized that serum ALB level is a significant independent biomarker for a broad spectrum of human diseases including cancer." (PMID 36831351, 2023). "Because HALP requires only a complete blood count and albumin - already routinely collected for cancer patients - HALP shows potential as a cost-effective biomarker to aid clinicians in improving outcomes for immuno-nutritionally deficient patients." (PMID 36848404, 2023). "mGPS, defined by serum CRP and albumin levels, is a simple and objective parameter for assessing cancer cachexia, focusing on nutrition and systemic inflammation." (PMID 37686634, 2023). "The decrease in serum albumin level can directly reflect the increase in protein consumption and the demand of patients with cancer." (PMID 36600242, 2023). "Along with genetic modifications, a wide range of targeted albumin nanoparticles loaded with anti-cancer drugs are designed using the chemical modifications of amino- and carboxylic groups." (PMID 36678860, 2023). "Fibrinogen and albumin are two acute-phase proteins induced in response to systemic inflammation but show opposite abundance trends under cancer inflammatory stimulation." (PMID 38031022, 2023). "Risk factors for short-term mortality due to FN include age, cancer type, comorbidities, delayed administration of antibiotics, and laboratory abnormalities (i.e., low serum albumin, anemia, and increased lactate dehydrogenase)." (PMID 37685702, 2023). "Significant relationships and differences of haemoglobin, CRP and albumin supports future use of these biomarkers in cancer cachexia." (PMID 37906352, 2023). "The prognostic nutritional index (PNI), which integrates lymphocyte count and serum albumin levels, is widely regarded as a comprehensive measure reflecting the nutritional and immunological status related to cancer." (PMID 37371699, 2023). "The combination of good biodegradation in cancer tissue and the long blood half-life of albumin can provide a possible enzyme-activatable 19F MRI probe, which warrants further investigation." (PMID 36838682, 2023). "Cancer patients often have hyper-catabolic, hyper-inflammatory, and malnourished states, which can inhibit albumin synthesis via elevated C-reactive protein." (PMID 37438683, 2023). "Index4 uses patient’s performance status, stage of cancer and two laboratory parameters (albumin and creatinine clearance) for calculation of an overall score." (PMID 36658198, 2023). "Albumin-based theranostic nano-probe HSA-Gd-IR825 was paired with photothermal ablation of lymph node metastases after surgery to provide a molecularly targeted imaging strategy for malignant tumours." (PMID 37375846, 2023).
cancer (continued). "Despite this, the clinical success of albumin NPs is exemplified by the FDA-approved drug Abraxane, which is an albumin-bound form of paclitaxel used for the treatment of various cancers." (PMID 38004601, 2023). "In consequence, cellular and biochemical blood markers of systemic inflammation, such as the neutrophil to lymphocyte ratio (NLR) and the albumin to globulin ratio (AGR) have been proposed as prognostic factors for human cancer development." (PMID 37396996, 2023). "In the same way that ferritin, albumin, and virus-like particles are effective against BC and CC, many natural downstream products are also effective against these cancers through different mechanisms of action." (PMID 38069380, 2023). "As a consequence, in cancer patients, measuring the levels of serum albumin in the blood can reflect the severity of the disease, the nutritional status, the disease progression, and the prognosis." (PMID 37836576, 2023). "It is known that albumin levels; lymphocyte count; and their ratios to hematological parameters, such as platelets and neutrophils, have prognostic importance in advanced cancer patients." (PMID 37685501, 2023). "In various medical fields, serum albumin (Alb) is used as a nutritional indicator and predictive marker for cancer prognosis and infectious diseases." (PMID 38137581, 2023). "The upregulated expression of FcRn was identified in a number of cancers, suggesting the importance of ALB recruitment driven by FcRn and the recycling and transcytosis of ALB regulated by FcRn." (PMID 35958556, 2022). "The Hemoglobin, Albumin, Lymphocyte, and Platelet (HALP) Score and the Geriatric Nutrition Risk Index (GNRI) are used as prognostic factors in different types of cancers." (PMID 36061883, 2022). "NAR, which combines the advantages of neutrophils and albumin, is a promising biomarker for predicting cancer prognosis." (PMID 36458178, 2022). "Baseline values of ΔS-Cys-Albumin in gastrointestinal cancer patients and cancer-free donors were determined." (PMID 36182099, 2022). "Cut-off values of these markers were lower than those used for other diseases due to the more favorable prognosis of GCTs compared to the other cancers and higher basal levels of albumin in these patients." (PMID 35756636, 2022). "Recent studies have shown the importance of single nutritional indices such as serum albumin in predicting poor outcomes in cancer patients." (PMID 35158991, 2022). "The preoperative serum albumin is a more objective biomarker that adequately reflects cancer cachexia." (PMID 36054114, 2022). "ALB is also closely related to the prognosis of a variety of cancers and can be used as a predictor of the recurrence, metastasis, and death of a variety of malignant tumors." (PMID 36290873, 2022). "Background and objective: Fibrinogen and albumin are two proteins widely used, singularly and in combination, in cancer patients as biomarkers of nutritional status, inflammation and disease prognosis." (PMID 36295649, 2022). "were the first to propose the FA score, calculated as the ratio of fibrinogen to plasma albumin, as a new prognostic marker in cancer." (PMID 36313734, 2022). "In our study, serum albumin level was possible to be affected by inflammation on cancer bringing condition." (PMID 36501212, 2022). "Among them, IL-6, TNF-α, IL-1β, CRP, and albumin are the most investigated, but the correlation between them and cancer cachexia is elusive in humans." (PMID 36158184, 2022). "Patients with cancer also tend to have lower serum albumin levels due to the hepatotoxic effects of chemotherapeutic agents or chronic malnutrition." (PMID 35672868, 2022). "Cancer (HR: 1.509 (1.212–1.879]), low serum albumin at CRRT (HR: 0.733 [9.628–0.855]), respiratory (HR: 1.277 [1.002–1.627]), and circulatory (HR: 1.504 [1.183–1.912]) failure upon hospital arrival were associated with increased in-hospital mortality." (PMID 35915412, 2022).
cancer (continued). "CRP and ALB were the most widely recognized prognostic indicators in various cancers, including ESCC." (PMID 35300627, 2022). "The results demonstrate that an F-base-directed ApDC-albumin complex is a potential platform for drug delivery and targeted cancer therapy." (PMID 36559275, 2022). "Decreased albumin levels indicated poor nutritional status, immune status and prognosis in cancer patient." (PMID 35481993, 2022). "Another important consideration is that cytokines, such as interleukin-1, interleukin-6, and tumor necrosis factor-α, inhibit the synthesis of albumin, and the levels of these cytokines are increased in patients with malignant tumors." (PMID 36316884, 2022). "The GNRI comprising serum albumin level and body weight and height is reported as a useful prognostic factor in several cancers." (PMID 35797279, 2022). "Future studies focusing on the performance of CRP/Albumin ratio in predicting overall survival in Chinese cancer patients are warranted." (PMID 36501196, 2022). "After accumulation based on the EPR effect, ADC–albumin complexes (approximately 21.2 nm in diameter, based on summation) would bind cancer antigens probabilistically to a greater degree than ADCs alone due to molecular size." (PMID 36546903, 2022). "Serum albumin was the main plasma protein indicating nutritional status, and lymphocyte was the essential component of immune system to eradicate cancer cells." (PMID 35354923, 2022). "In the past, body mass index (BMI) and serum albumin (ALB) were often used to assess the nutritional status of cancer patients." (PMID 36145159, 2022). "In total, low albumin levels and low BMI should therefore certainly negatively impact the survival in cancer patients." (PMID 36297021, 2022). "Other combinations of anticancer drugs, including paclitaxel and pirarubicin, paclitaxel and all-trans-retinoic acid, or docetaxel and gemcitabine, have been examined for their co-binding to albumin nanoparticles and application in cooperative cancer therapy." (PMID 35456562, 2022). "In contrast to the EPR effect, SPARC-related spontaneous uptake by cancer cells occurs selectively for the albumin." (PMID 35456562, 2022). "Higher cancer-related inflammation increases the depletion of serum albumin and impairs the synthesis of albumin within the liver, contributing to a high HS-mGPS." (PMID 35242712, 2022). "The research has shown that lower serum albumin level was an independent prognostic factor of long-term survival in a variety of cancers." (PMID 36105255, 2022). "In our study, we loaded the Ap onto ChNPs, then coated them with albumin-folic to produce water-soluble nanoparticles and targeted the cancer cells by increasing the penetration of Ap inside the HePG-2 cell." (PMID 35745733, 2022). "In clinical practice, nutritional status in cancer patients is often assessed by monitoring albumin levels." (PMID 35629338, 2022). "Low albumin levels can be used as a predictor for the survival of cancer patients who underwent chemotherapy and radiation." (PMID 34846716, 2022). "GPS, which is estimated with CRP and the albumin level which demonstrates the presence of systemic and local inflammation, has also been identified as a prognostic indicator for both survival and cancer progression." (PMID 34845844, 2022). "In conclusion, the introduction of palmitic acid as an albumin binder can be a promising strategy to promote small molecule peptide-based radiopharmaceuticals for targeted radiotherapy of cancer." (PMID 35890224, 2022). "In cancer chemotherapy, Abraxane® (albumin-added paclitaxel), liposomal formulations containing irinotecan and daunorubicin/cytarabine, and ADCs have been commercialized, and other micelle formulations are under development." (PMID 35458072, 2022). "Based on the assembly and biomineralization process of albumin, batched albumin-related nanostructures can be facile fabricated for theranostic application of cancer." (PMID 35414075, 2022).
cancer (continued). "Inflammatory cytokine levels surge as cancer cells progress, resulting in the albumin synthesis suppression, degradation promotion, and capillary escape." (PMID 36458177, 2022). "Monoclonal antibodies and albumin-bound nanoparticles are examples of FcRn-dependent anti-cancer therapeutics." (PMID 35806069, 2022). "Albumin (ALB) as an independent prognostic indicator of cancer survival has been established in previous studies." (PMID 36531036, 2022). "Several studies have identified assessed serum albumin as a possible survival predictor in patients with malignant tumors, as shown in the review by Gupta and collaborators." (PMID 35052870, 2022). "Blood markers such as albumin and prealbumin can predict outcomes in cancer patients undergoing surgery." (PMID 36497352, 2022). "In short-term survival analysis (12 months), albumin level was also an independent prognostic factor, which is consistent with the results of previous studies in cancer patients." (PMID 35041664, 2022). "FAR, which reflects the ratio of fibrinogen to albumin, has been a candidate to be a good prognostic factor in many cancers in recent years." (PMID 36496365, 2022). "Overall, these results are consistent with the fact that ΔS-Cys-Albumin in the serum of cancer patients started (at baseline) at significantly higher values than in the serum of cancer-free donors." (PMID 36182099, 2022). "There is also a close relationship between serum albumin levels and systemic inflammation in patients with cancer." (PMID 36458177, 2022). "At present, a large number of clinical trials of albumin paclitaxel in cancer treatment have shown that albumin paclitaxel has sound antitumor effects." (PMID 35719323, 2022). "Evidence implies that plasma fibrinogen and serum albumin level (FA score) based on plasma fibrinogen and serum albumin is related to cancer prognosis." (PMID 36313734, 2022). "Red blood cell distribution width (RDW) to albumin ratio (RAR) is associated with poor prognosis in diabetic comorbidities and cancer." (PMID 36211519, 2022). "The emergence of a systemic inflammatory state in cancer, reflected by elevated CRP levels, is often accompanied by a decrease in serum albumin concentration, sustained weight loss, impaired nutritional status, and increased mortality." (PMID 36585638, 2022). "The nomogram included chronic respiratory disease, chronic kidney dysfunction, malignant tumor, abnormal neutrophil count, abnormal lymphocyte count, decreased serum albumin level, and increased HbA1c level." (PMID 36344933, 2022). "The modified Glasgow prognostic score (mGPS), which incorporates both serum CRP (cutoff: 10 mg/L) and albumin (cutoff: 35 g/L) levels, is an independent overall survival (OS) and cancer-specific survival predictor in OSCC." (PMID 35242712, 2022). "A low serum albumin level was reported as a significant independent predictive factor for PFS in cancer patients." (PMID 35965580, 2022). "Most nutrition assessment biomarkers are based on serum albumin and body weight, which have been reported to be effective in assessing the prognosis of patients with various cancers." (PMID 36517779, 2022). "Previous evidence reported that tumor necrosis factor can mediate the chronic consumption of albumin in patients with malignant tumors, resulting in HAE syndrome." (PMID 35850629, 2022). "Human serum albumin (HSA) can be internalized into cancer cells, where its degradation contributes to the supply of free amino acids, representing a major energy source for tumors." (PMID 35416106, 2022). "This review introduces representative protein nanoparticles applicable in cancer theranostics, including virus-like particles, albumin nanoparticles, silk protein nanoparticles, and ferritin nanoparticles." (PMID 34997888, 2022). "The serum ALB is the simplest and most efficient index that can reflect the body's nutritional condition and is the decisive factor in the immune response of cancer cells." (PMID 35990994, 2022).